RNU6-965P (RNA, U6 small nuclear 965, pseudogene)
Gene: Small nuclear RNA gene on chromosome 1 (101,728,642 to 101,728,737, reverse strand). Ensembl gene ENSG00000252530.
Homologues: Orthologues: chimpanzee U6 (98% identical), dog U6 (61% identical), rat LOC120099052 (56% identical). Paralogues in human: RNU6-836P (78% identical), RNU6-1074P (76% identical), RNU6-966P (76% identical), RNU6-1152P (75% identical), RNU6-1289P (75% identical), RNU6-140P (75% identical), RNU6-211P (75% identical), RNU6-214P (75% identical), RNU6-417P (75% identical), RNU6-102P (74% identical), RNU6-1081P (74% identical), RNU6-1235P (74% identical), and 1287 more.